NOMO3 (NODAL modulator 3)
Description:
Component of the multi-pass translocon (MPT) complex that mediates insertion of multi-pass membrane proteins into the lipid bilayer of membranes. The MPT complex takes over after the SEC61 complex: following membrane insertion of the first few transmembrane segments of proteins by the SEC61 complex, the MPT complex occludes the lateral gate of the SEC61 complex to promote insertion of subsequent transmembrane regions.
Synonyms: Nomo
Tractability: Antibody: UniProt predicts a signal peptide or a membrane-spanning region. PROTAC: ubiquitination databases record sites on it.
Gene: Protein-coding gene on chromosome 16 (16,232,506 to 16,300,806, forward strand). Ensembl gene ENSG00000103226.
Subcellular location: Endoplasmic reticulum membrane
Gene Ontology:
Molecular function: protein binding; ribosome binding; carbohydrate binding
Biological process: multi-pass transmembrane protein insertion into ER membrane; determination of left/right asymmetry in lateral mesoderm; negative regulation of nodal signaling pathway
Cellular component: endoplasmic reticulum membrane; multi-pass translocon complex
Genetic constraint (gnomAD): Loss-of-function variants: 10 observed, 29.7 expected, observed/expected ratio (o/e) 0.34, 90% interval 0.21 to 0.57. The synonymous counts are far from expectation, so gnomAD's model fits this gene poorly and the ratio says little. Missense variants: 133 observed, 301.56 expected, observed/expected ratio (o/e) 0.44, 90% interval 0.38 to 0.51. Synonymous variants: 52 observed, 108.42 expected, observed/expected ratio (o/e) 0.48, 90% interval 0.38 to 0.6.
Homologues: Orthologues: rat Nomo1 (93% identical), mouse Nomo1 (92% identical), tropical clawed frog nomo3 (78% identical), zebrafish nomo (69% identical), Drosophila melanogaster CG1371 (31% identical), Caenorhabditis elegans nra-4 (24% identical). Paralogues in human: NOMO2 (99% identical), NOMO1 (99% identical).
Diseases named in the same sentence as NOMO3 in open-access papers:
NOMO3 is named in the same sentence as 1 disease in open-access papers, as found by Europe PMC text mining. Sharing a sentence is not in itself a finding about the gene and the disease. The quoted sentences say what the papers report.
cancer (1 paper, 2019). A tumor composed of atypical neoplastic, often pleomorphic cells that invade other tissues. "A review of the literature revealed that aberrant expression of CKMT1A, GCNT1, NCALD, NFKBIB, NOMO3/Nodal, SLC16A5, or TRPV2 was correlated with cancer." (PMID 31363162, 2019).